IL1B (interleukin 1 beta)
Diseases named in the same sentence as IL1B in open-access papers (continued):
Sharing a sentence is not in itself a finding about the gene and the disease.
cancer (continued). "Post-anti-cancer therapies, dying cancer cells release ATP and activate P2X7R in DCs, leading to IL-1β secretion via P2X7R-dependent NLRP-3 inflammasome assembly, and this suggests the role of NLRP-3 inflammasome in the efficacy of anti-cancer therapies." (PMID 36741002, 2023). "Their investigative focus encompassed a suite of biomarkers—activin A, growth differentiation factor 15 (GDF-15), IL-6, interleukin-1 beta (IL-1β), and tumor necrosis factor alpha (TNF-α)—which provided a comprehensive view of cancer cachexia’s unfolding." (PMID 37755304, 2023). "Aconitine alkaloids have been shown to promote the secretion of cytokines like TNF-α, IL-1β, and IFN-γ in cancer model mice, thereby enhancing the immune function of the body." (PMID 37180714, 2023). "Pro-inflammatory mediators, such as TNF-α, IL-6, IL-1B, and MCP-1, are involved in the secondary activation of many genes involved in the pathogenesis of inflammation and cancer." (PMID 37103287, 2023). "We identify cancer cell VCAN and myeloid IKKβ as the accomplices of KRAS that trigger secretion of IL-1β in the milieu of KRAS-mutant cancers." (PMID 36980752, 2023). "Adipocytes secrete many adipokines, cytokines, and chemokines (i.e., IL-1b, TNF-α, IL-6, TGF-β) that affect inflammation and fibrosis which promote cancer development." (PMID 37491420, 2023). "Here, it was observed that the expression of IL-6, IL-10, IL-1β and VEGF were found to be significantly upregulated in supernatant from MDSC in comparison to cancer cell supernatant." (PMID 38304256, 2023). "From the Elisa results, BMDCs in LT and LRT groups secreted higher amounts of IL-6, TNF-α, IL12p70, and IL-1β than in other groups, indicating the successful DCs maturation by upregulating CRT expression on cancer cell’s surface." (PMID 37951973, 2023). "Yet, several investigations have indicated that IL‐1β, IL‐18, and HMGB1 have a suppressive impact on cancer." (PMID 37752941, 2023). "Our own studies confirm the influence of cytokines (i.e., concentrations of IL-1A, IL-1B, IL-2, IL-6, IL-10, TNF, and IL-4) on the emergence of fatigue in all its dimensions in patients with cancers of the reproductive organs at various stages of treatment." (PMID 36834426, 2023). "Recent studies have shown that pro-inflammatory cytokines such as interleukin (IL)-1β, tumor necrosis factor (TNF)-α, and IL-6 in a tumor microenvironment contribute to the development and metastasis of cancers through the immune escape of cells [2, -4]." (PMID 37501379, 2023). "This suggests that IL-1β–induced ERK and NF-κB signaling induces cancer cell migration and invasion by regulating PAK1 phosphorylation." (PMID 38188678, 2023). "Elevated levels of IL-1β, IL-6, and TNF-α impair systemic insulin sensitivity and promote cancer development." (PMID 37175211, 2023). "In cancer and inflammatory diseases, the major inflammasome is TNF-α, which activates the NF-κB pathway, whereas the minor inflammasomes are IL-1β, CCL2, and CCL5." (PMID 36139553, 2022). "After cancer cell colonization, TGF-β2 induced by IL-1β promotes PCa cell dormancy via activation of TGFBR3–p38 MAPK signaling." (PMID 36237303, 2022). "Based on our in vitro experiments that stimulate cancer cells, it appears that individual factors act in a cell-specific manner; in CMT cells, TNFα is the dominant factor, whereas in EA1 cells IL-1β is the most potent." (PMID 36686777, 2022). "IL-1β is capable of regulating epithelial-mesenchymal transition (EMT) and is involved in cancer development and distant metastasis." (PMID 36264639, 2022). "IL1A and IL1B are key cytokines that regulate inflammation and influences TME, thus promoting the origin and progression of various cancers." (PMID 35296025, 2022). "In the present study, we detected the levels of IL-1α, IL-1β, and TGF-β in AGS and SW480 cancer cell media and found that TGF-β level was increased significantly in both cancer cell media." (PMID 35265687, 2022).
cancer (continued). "Chanling Gao exerted the analgesic effects in the cancer-induced bone pain (CIBP) rat model by inhibiting the IKKβ/NF-κB signaling pathway and the synthesis and release of TNF-α, IL-1β, and IL6." (PMID 36415861, 2022). "On the other hand, some inflammatory factors (IL-1β, IL18, and HMGB1) released by pyroptosis can trigger the activation of cancer-promoting signaling pathways including ERK1/2, p38 MAPK, and VEGF pathways." (PMID 35368686, 2022). "Of interest, TRIB1 knockdown in MDMs (MTRIB1-KD) enhanced expression of IL1β and TNF mRNA, emphasizing that cancer cell secreted factors that were used to re-educate MTRIB1-KD to TAMTRIB1-KD are effectively altering the phenotypes of these cells." (PMID 35664073, 2022). "Peiminine downregulates the expression of inflammatory cytokines in cancer cells, decreasing the levels of COX-2, TNF-α, IL-1β, as well as suppressing NF-κB signaling." (PMID 36582529, 2022). "Proinflammatory cytokines such as TNF-α, IL-6, IL-1β, TGF-β, and IFN-γ modulate PD-L1 expression in both cancer and stromal cells." (PMID 35326493, 2022). "● Increased IL-1β levels are a poor prognosis marker.● Activates IRAK4 and NF-κB, supports cancer progression and chemoresistance." (PMID 36465353, 2022). "According to numerous findings, TNF-α is elevated in various cancers, with higher levels in preneoplastic and neoplastic tissues, similarly to the way TNF-α-induced inflammation is exhibited by IL-1β, a pro-inflammatory cytokine." (PMID 36294905, 2022). "NETs enhance the expression of EMT markers ZEB1, Snail and fibronectin, cancer stem cell marker CD44, proinflammatory mediators, such as IL1β, IL6, IL8, CXCR1, MMP2 and MMP9." (PMID 35574410, 2022). "The amount of TGF-β was significantly higher than IL-1α and IL-1β in AGS and SW480 cancer cell media." (PMID 35265687, 2022). "A QD3-mediated senolytic effect was accompanied by decreased SA-beta galactosidase activity and the levels of p27, IL-1β, IL-8, and HSP70 in cancer cells." (PMID 35158873, 2022). "IL-1β induces ZEB1, a mediator of EMT formation, and ICAM-1 expression, which promotes adhesion and self-renewal of cancer stem cells (CSC)." (PMID 35884974, 2022). "Researches reveal that under proinflammatory cytokines and chemokines, tumor necrosis factors and IL1b can activate CXCR4 receptors on prostate cancer cells to facilitate the invasion and metastasis of cancer cells." (PMID 36439106, 2022). "The concomitant effects of IL-18, IL-1β and NLRP3 elevation were ignored in studies claiming that GSDMD mediates pyroptosis in cancer cells." (PMID 36091247, 2022). "As knockdown of NEK7 alone was sufficient to induce pyroptosis by mediating GSDMD-N and IL-1β release, these results suggested that NEK7-regulated HCC cell pyroptosis inhibited HSC activation and cancer–stromal interaction." (PMID 35223495, 2022). "During cancer development, it is stimulated by long-term inflammatory factors and cytokines (e.g., high levels of GM-CSF, VEGF, IL-6, IL-1β, adenosine, HIF1α)." (PMID 36131911, 2022). "NETs induce gene expression of cancer stem cell marker CD24, and proinflammatory factors, such as IL1β, IL6, IL8, CXC motif chemokine receptor 1 (CXCR1), MMP2, MMP9 in cocultured luminal breast cancer cells." (PMID 35574410, 2022). "As such, while other studies have found that IL-6, IL-1b, and CRP is significantly up-regulated in specific groups of cancer patients exhibiting poor sleep, this/these biomarker(s) did not correlate significantly with sleep quality in our broader cohort." (PMID 36213755, 2022). "In summary, we showed that KRAS-mutant cancer cells express CCL2 and IL1R1 to initiate an inflammatory signaling loop with CCR2/IL-1β-expressing myeloid cells." (PMID 35327394, 2022). "S100A8 also significantly reduced protein levels of IL-6, IL-1β and IL-12β in BALF from mice with LLC cancers (p < 0.05)." (PMID 35655772, 2022).
cancer (continued). "Because osteopontin (OPN), IL‐1β, tumor necrosis factor (TNF)‐α, and IL‐6 are well‐known growth factors derived from macrophages, cancer cells were stimulated with these recombinant proteins, and cell proliferation was assessed with the WST assay." (PMID 35132816, 2022). "The increase of TNF, IL-1β, and IL-10 secretion in healthy colonocytes (V BM alone and with hPA120 treatments; p < 0.05) and for TNF and IL-10 in cancer cells (treatments except O BM + hPA120 and V BM, respectively; p > 0.05) were stated." (PMID 36296918, 2022). "Many inflammatory factors like IL-1β, TGF-β, IL-6 can regulate the DNA methylation patterns that induce cancer initiation and progression in cancers such as gastric cancer, ovarian cancer, and liver cancer." (PMID 36225315, 2022). "Using depletion experiments and knock-out mice, it was shown that the MDSC-derived IL1-β triggers IL17 production by CD4+ T cells, limiting the anti-cancer efficacy of 5-FU." (PMID 35742825, 2022). "It is possible that clinical trials based on elevated biomarker levels (such as IL-1β, IL-6, or TNF) in each individual patient will allow a more targeted approach to ameliorating cancer cachexia." (PMID 36358681, 2022). "More recently, swimming has been shown to attenuate tumor growth and cancer-related muscle atrophy by downregulating the expression of proinflammatory proteins including NF-κB, p-NF-κB, TNF-α, IL-1β, and IL-6." (PMID 36505042, 2022). "To investigate the relevance of our findings to KRAS-mutant human cancers, we analyzed the average expression of KRAS, CCL2, and IL1B genes in public data (GSE43458) from the BATTLE trial." (PMID 35327394, 2022). "Potential activity of purified CCL21/IL1β in stimulating the proliferation and migration of MCF7 cancer cell line was investigated using the wound healing method." (PMID 36037155, 2022). "As shown in the present study, EGCG inhibits IL-1β-induced uPAR upregulation, suggesting that EGCG delays cancer progression by inhibiting the inflammatory response." (PMID 36430487, 2022). "With cytokines such as the IL-1β, IL-6, and TNF all having pro-angiogenic properties, it is clear that inflammation and angiogenesis are related to cancer." (PMID 35626056, 2022). "Meanwhile, there were pieces of evidences that the inflammation induced by IL-6 and IL-1β was through the MAPKs, NF-ΚB, and STAT3 pathways in many cancers." (PMID 35280511, 2022). "Resveratrol nanoparticles can inhibit the growth, proliferation and migration of cancer stem like cells by inducing M1-like macrophages producing inflammatory cytokines such as TNF-α, IL-6 and IL-1β." (PMID 36439106, 2022). "At the promotion stage, inflammatory cytokines (notably TNF, IL-1β and IL-6) induce NF-κB and STAT3 transcription factors in cancer cells, which activate genes controlling cell survival, proliferation and growth." (PMID 35406394, 2022). "GSDMC, NLRP7, CASP5, PYCARD, IL18, IL1B and GSDMA were significantly upregulated in 22, 18, 18, 18, 18, 16 and 17 types of cancers, respectively." (PMID 35246158, 2022). "Our experimental approach exploits the paracrine up-regulation of CCL2, CCL5, IL-1β, and IL-6 in ADMSC in response to TNBC cells secretome, confirming and complementing prior co-culture approaches mixing cancer cells and adipocytes." (PMID 35268073, 2022). "On the one hand, inflammatory factors released accompanying cancer cell pyroptosis form a chronic inflammatory microenvironment, including NLRP3, IL-18 and IL-1β." (PMID 36091247, 2022). "We selected the eleven cytokines that were significantly increased in cancer (GMCSF, IL-6, IL-1β, Rantes/CCL5, MIP1α, MIP1β, TNFα, MCP1/CCL2, IL-8, IL-12p40, IL10) and selected all the positive Pearson's correlations with r > 0.8 and significance of p < 0.01." (PMID 35048057, 2021). "In particular, IL-1β extends the survival of endothelial cells by stimulating the production of VEGF by vascular smooth muscle cells and contributes to cancer invasiveness by activating STAT3." (PMID 34944856, 2021).
cancer (continued). "To determine if persistent TNFα + IL-1β stimulation modifies invasion-related functions in TNBC cells, we analyzed the ability of the cancer cells to undergo epithelial-to-mesenchymal transition (EMT)." (PMID 34072893, 2021). "Additionally, the increased production of pro-inflammatory cytokines such as IL-1b, IL-6, IFNa2, and TNFa, amongst others, is critical to the development of the host response to foreign microorganisms, the vaccine-based immune response, and the response to cancer immunotherapy." (PMID 33807734, 2021). "Extracellular ATP, released in TME by cancer cells and infiltrating inflammatory cells, interacts with P2X7R expressed by DCs to stimulate IL-1β release, which in turn increase CD4+ and CD8+ T cells, mediating antitumor responses." (PMID 33806300, 2021). "The anti-cancer effects of AA phyto-extracts could be attributed to the presence of casticin and chrysosplenol D, which were found in greater amounts in our samples and are able to inhibit the cell migration and pro-inflammatory cytokine production (i.e., IL-1β, IL-6, and MCP-1) induced by LPS." (PMID 34356599, 2021). "Pro-inflammatory cytokines, such as interleukin (IL)-6, IL-1β, and tumor necrosis factor-α (TNF-α), promote cancer progression." (PMID 34833849, 2021). "CH13L1 promotes inflammatory cytokine production (including TNF-α, IL-1β, IL-6, and IFN-γ), connective tissue growth, fibrosis, and cancer proliferation." (PMID 33498689, 2021). "In the present study, we also observed that the pro-inflammatory cytokines that promote cancer progression, namely, IFN-γ, TNF-α, IL-1β, IL-6, IL-8, and IL-12, were decreased." (PMID 33869169, 2021). "The present study shows that CK2 down-regulation induces the nuclear import of NF-κB by reducing the IκB levels, which promotes the subsequent expression of SASP factors, such as IL-6, IL-1β, and MMP3 in human cancer cells." (PMID 33401686, 2021). "cBioPortal was used to investigate the specific genetic alterations of KLF4 and IL-1β in NSCLC dataset (TCGA, Pan Cancer Atlas) with 1144 patient samples (660 LUAD + 484 LUSC)." (PMID 34440860, 2021). "Regulates cancer cells' survival, growth, and invasion through producing tissue remodeling molecules, including MMP-2, 9, TNF-α, CXCL10, and IL-1β.Protects cancer cells from cytotoxic effects of radiotherapy and anticancer agents." (PMID 35096289, 2021). "Many inflammatory factors such as interleukin-1beta (IL1b), interleukin-17a (IL17a) and interleukin-6 (IL6) have been reported to facilitate HCC progression by promoting proliferation, metastasis and cancer stem cells (CSCs) formation." (PMID 33661757, 2021). "MDSC-secreted factors that overlap with TREM-1 target genes, including IL-1β, TNF-α, IL-8 and IL-6, have been reported to promote angiogenesis and induce cancer cell migration, invasion, and survival." (PMID 34956864, 2021). "We contribute to highlight the cooperation between TAM and NK cells through the secretion of IL-1β, TNF-α and IFN-γ, leading to the production of CCL22 by cancer cells." (PMID 33924428, 2021). "When cancer cells were co-cultured with TAM, we found that the expression of NLRP3, AIM2, cleaved-caspase 1, and IL-1β was significantly upregulated." (PMID 34815793, 2021). "Following RARβ silencing, the down-regulation of cancer-related genes, ALDH1A1, CYP24A1, BIRC5, EDN1, IL-1β and PTGS2 in A549 parental cell suggest the importance of RARβ in controlling the expression of genes related to carcinogenicity." (PMID 33995625, 2021). "This IL-6 expression was dependant on TG2 upregulated through NF-kB, PI3K-, and JNK-dependent signalling cascades in promoting a cancer stem cell phenotype and inducing the EMT and metastasis when amplified by Interleukin 1 beta (IL1B) production." (PMID 34205140, 2021).
cancer (continued). "In contrast, gallic acid equivalent (GAE) treatment increased intracellular ROS production in human cancer colon fibroblast cells and decreased the expression levels of TNF-α, IL-1β, IL-6, and NF-κB to suppress cell proliferation." (PMID 33664749, 2021). "Similar analysis including IL-1β, Rantes/CCL5, MCP1, GMCSF, TNFα, and IL-6 showed similar results with elevated IL-6 increasing the probability of having a cancer diagnosis (p < 0.0046)." (PMID 35048057, 2021). "Logistic regression analysis including the eight cytokines increased in cancer compared to control (GMCSF, IL-1β, IL-6, IL-8, Rantes/CCL5, MIP1α, TNFα, MCP1) was performed." (PMID 35048057, 2021). "Asmany interfering factors are assay-specific, we have explored matrixinterference for a range of enzymatic immunoassays, including a directmIgG/anti-mIgG, a sandwich cancer biomarker PSA, and a sandwich inflammatorycytokine IL-1β." (PMID 34138534, 2021). "The induction of aerobic glycolysis by LMP1 leads to increased secretion of IL-1β, IL-6, IL-18, and GM-CSF, which in turn promotes MDSC differentiation and expansion as well as cancer cell proliferation and resistance to apoptosis." (PMID 33718235, 2021). "This was followed by development of the gold standard cytokine cocktail comprising IL‐1β, IL‐6, TNFα, and PGE2, as maturation signals for DCs;93, 94 however, MoDCs derived using this cocktail proved ineffective for cancer immunotherapy." (PMID 32663904, 2021). "For the purpose of correlation analysis we have retrieved data on systemic concentrations of IL-1β, IL-4, IL-6, IL-8, IL-12p70, FGF2, G-CSF, GM-CSF, MCP-1, MIP-1α, PDGF-BB, TNFα, and VEGF-A, available for 43 of our cancer patients." (PMID 33020452, 2020). "Another study showed that IL-1β expressed in OSCC cells leads to CXCL1 production by CAFs, which in turn promotes cancer cell migration." (PMID 32635472, 2020). "The nuclear factor kappa B (NF-κB) signaling pathway and its downstream inflammatory factors interleukin-6 (IL-6), interleukin-1β (IL-1β), and tumor necrosis factor-α (TNF-α) play an important regulatory role in the developmental process of cancer pain." (PMID 32431607, 2020). "c-jun and c-Fos are target genes for the treatment of inflammation, cancer, and vascular reconstruction and can regulate the expression of many downstream genes, such as CCL2 and IL-1β." (PMID 33273957, 2020). "In particular, statins plus IL-2 increased IL-1β and IL-18 production in CD56+ DC/macrophage-like cells, which in turn cooperate with IL-2 to induce IFNγ release by NK cells, dampening cancer progression." (PMID 32823961, 2020). "This pattern appears correspondent with the known biological conditions typically induced by metastatic cancer cells as the immunosuppressive function (IL-10), vasculogenic action (VEGF), and hypoxic condition (IL-1b)." (PMID 32630302, 2020). "IL-1β is able to regulate metastasis at various levels, for example, by regulating (EMT), cancer cell stemness, sphere formation, or migration/invasion." (PMID 32635472, 2020). "Flavonoids have been reported to induce apoptosis of human cancer cells, inhibit NF-κB and the IL-6/STAT3-mediated inflammatory signalling pathway, and also regulate levels of inflammatory cytokines such as IL-6, IL-1β, and TNF-α." (PMID 33082817, 2020). "In an inflammation-driven cancer setting, we previously reported that myeloid S1PR1 signaling induces IL-1β production by enhancing NLRP3 (NOD-, LRR- and Pyrin Domain-Containing Protein 3) inflammasome activity." (PMID 32630814, 2020). "A crucial step in IL-1β-induced signaling pathways, leading to EMT and other pathways involved in cancer progression, is the increased phosphorylation of AKT(ser 473), a component of the protein complex PI3K/AKT." (PMID 32244518, 2020). "IL-1β is also an important cytokine, recently described in PDAC cancer, that drives inflammatory CAF phenotype (iCAF) phenotype in from resident pancreatic stellate cells." (PMID 32957515, 2020).